COL4A5 (collagen type IV alpha 5 chain)
Description:
Type IV collagen is the major structural component of glomerular basement membranes (GBM), forming a 'chicken-wire' meshwork together with laminins, proteoglycans and entactin/nidogen.
Synonyms: ASLN; ATS; ATS1; CA54
Tractability: Small molecule: a structure with a bound ligand is known. Antibody: its Gene Ontology location is reachable by antibodies, with high confidence; UniProt places it where antibodies can reach, with medium confidence; UniProt predicts a signal peptide or a membrane-spanning region; the Human Protein Atlas places it where antibodies can reach. Other modalities: an approved drug acts on it.
Gene: Protein-coding gene on chromosome X (108,439,745 to 108,697,547, forward strand). Ensembl gene ENSG00000188153.
Subcellular location: Secreted, extracellular space, extracellular matrix, basement membrane
Subcellular location (Human Protein Atlas): Plasma membrane; Vesicles; Predicted to be secreted
Pathways (Reactome):
Extracellular matrix organization: Anchoring fibril formation; Assembly of collagen fibrils and other multimeric structures; Collagen biosynthesis and modifying enzymes; Collagen chain trimerization; Collagen degradation; Crosslinking of collagen fibrils; ECM proteoglycans; Fibronectin matrix formation; Integrin cell surface interactions; Laminin interactions; Non-integrin membrane-ECM interactions
Developmental Biology: NCAM1 interactions; Regulation of expression of SLITs and ROBOs
Disease: Attachment of bacteria to epithelial cells
Signal Transduction: Signaling by PDGF
Gene Ontology:
Molecular function: extracellular matrix structural constituent conferring tensile strength; extracellular matrix structural constituent
Biological process: collagen fibril organization; extracellular matrix organization
Cellular component: basement membrane; extracellular matrix; collagen type IV trimer; endoplasmic reticulum lumen; extracellular region; collagen trimer; neuromuscular junction
Gene-disease validity (ClinGen):
ClinGen rates the evidence that COL4A5 causes each of these diseases.
Alport syndrome (X-linked): Definitive. A rare renal disease characterized by glomerular nephropathy with hematuria progressing to end-stage renal disease (ESRD), frequently associated with sensorineural deafness, and occasionally with ocular anomalies.
Homologues: Orthologues: chimpanzee COL4A5 (99% identical), macaque COL4A5 (99% identical), pig COL4A5 (95% identical), dog COL4A5 (94% identical), rabbit COL4A5 (94% identical), mouse Col4a5 (91% identical), rat Col4a5 (91% identical), guinea pig COL4A5 (87% identical). Paralogues in human: COL4A1 (61% identical), COL4A3 (53% identical), COL4A6 (49% identical), COL4A2 (47% identical), COL4A4 (40% identical), COL7A1 (38% identical), COL5A1 (36% identical), COL11A1 (36% identical), COL11A2 (35% identical), COL5A3 (34% identical), COL2A1 (33% identical), COL1A1 (33% identical), and 25 more.
Diseases named in the same sentence as COL4A5 in open-access papers:
COL4A5 is named in the same sentence as 146 diseases in open-access papers, as found by Europe PMC text mining. Sharing a sentence is not in itself a finding about the gene and the disease. The quoted sentences say what the papers report.
Alport syndrome (214 papers, 2004 to 2026). "Here, we present a case of a pregnant woman who was found to have X-linked Alport Syndrome with a heterozygous c.3587G>A (p.Gly1196Glu) mutation in the COL4A5 gene." (PMID 41799611, 2026). "She had genetically confirmed X-linked COL4A5 Alport syndrome and uncontrolled hypertension despite four antihypertensive medications." (PMID 41657422, 2026). "On the genetic front, hundreds of gene variants can cause or drive the progression of CKD, such as variations in the PKD1 and PKD2 genes in patients with polycystic kidney disease, and COL4A5 gene variants in those with Alport syndrome." (PMID 41598767, 2026). "Genetic testing revealed a heterozygous c.3587G>A (p.Gly1196Glu) mutation in the COL4A5 gene, consistent with X-linked Alport Syndrome." (PMID 41799611, 2026). "Another four patients were diagnosed with Alport syndrome: three of these presented with de novo missense mutations in the COL4A5 gene, and one patient had a mutation in the COL4A3 gene." (PMID 41828581, 2026). "Pathogenic variants in type IV collagen genes (COL4A3, COL4A4, COL4A5) are classically associated with Alport syndrome (AS), a hereditary nephropathy primarily affecting the glomerular basement membrane (GBM)." (PMID 40565535, 2025). "Genetic counseling was offered due to similar symptoms in maternal siblings, and molecular genetic testing (performed in India) confirmed a COL4A5 mutation in the patient and three maternal siblings, establishing the diagnosis of X-linked Alport syndrome." (PMID 39981328, 2025). "The syndrome is caused by mutations in type IV collagen genes (COL4A3, COL4A4, or COL4A5), with X-linked Alport syndrome (XLAS) accounting for approximately 80% of cases." (PMID 40852417, 2025). "One patient had familial FSGS, five had Alport syndrome with mutations in COL4A5 (four) and COL4A3 (one), one had PAX2 mutation, one NUP150 mutation and nephrotic range proteinuria, and one a variant in CLCN5 causing Dent Disease." (PMID 39950157, 2025). "Females with heterozygous COL4A5 variants are not only asymptomatic carriers of X-linked Alport syndrome but also face an increased risk of CKD, early- or late-onset ESRD, and extrarenal manifestations." (PMID 40004525, 2025). "Approximately 85% of patients with Alport syndrome (AS) have X-linked Alport syndrome (XLAS) from mutations in the COL4A5 gene." (PMID 40406358, 2025). "The COL4A5 gene resides on the X chromosome and causes X-linked Alport syndrome, while the COL4A3 and COL4A4 genes are both located on chromosome 2, resulting in an autosomal dominant or recessive mode of inheritance." (PMID 40004525, 2025). "Pathogenic variants in COL4A3 and COL4A4 cause autosomal forms of Alport syndrome (autosomal dominant or recessive), while pathogenic variants in COL4A5 cause X‐linked Alport syndrome." (PMID 40317772, 2025). "Among the most significant findings, COL4A3 and COL4A5 mutations were the most frequently detected, underscoring Alport Syndrome as the predominant genetic kidney disorder in this cohort." (PMID 41288877, 2025). "Three patients from Family 1 (P1–P3) harbored a hemizygous COL4A5 pathogenic variant (c.4706G > A), consistent with X-linked Alport syndrome." (PMID 41288877, 2025). "Among these diseases, X-linked Alport syndrome (XLAS) is a hematuric nephropathy affecting the glomerular basement membrane (GBM) secondary to pathogenic variations in the COL4A5 gene encoding the α5 subunit of type IV collagen [α5(IV)]." (PMID 41411050, 2025). "A dual-plasmid CRISPR-Cas9 system has been developed to correct pathogenic variants in the COL4A3 and COL4A5 genes associated with Alport syndrome." (PMID 40790091, 2025). "Alterations in the COL4A3, COL4A4 and COL4A5 genes are associated with glomerular basement membrane-related diseases, such as autosomal recessive Alport syndrome, familial focal segmental glomerulosclerosis, and thin basement membrane nephropathy." (PMID 40351420, 2025).
Alport syndrome (continued). "X-linked Alport syndrome (XLAS) caused by X-linked COL4A5 gene mutation is a hereditary disease that affects mainly the kidney." (PMID 40075271, 2025). "The X-linked form (XLAS), resulting from COL4A5 mutations, represents the most common type and accounts for approximately 80% of all Alport syndrome cases." (PMID 41516147, 2025). "The X-linked form of Alport syndrome is caused by variants in the COL4A5 gene, and the autosomal form is caused by variants in COL4A3 or COL4A4." (PMID 40392259, 2025). "The majority (57%) were located in the COL4A5 gene, reflecting the predominance of X-linked inheritance in Alport syndrome, while variants in the COL4A3 (19%) and COL4A4 (24%) genes accounted for autosomal forms of the disease." (PMID 40004525, 2025). "This study highlights the significant role of mRNA splicing mutations in the COL4A5 gene in Alport syndrome, particularly with 38.5% of SNVs affecting mRNA splicing and leading to more severe clinical phenotypes." (PMID 40567900, 2025). "In summary, identifying P/LP variants in COL4A3, COL4A4, or COL4A5 during reproductive carrier screening provides an important opportunity for early clinical intervention for Alport syndrome heterozygotes and their families." (PMID 40317772, 2025). "Our study provides important insights into the genetic landscape of Alport syndrome, confirming the central role of COL4A5 variants in X-linked inheritance and the involvement of COL4A3 and COL4A4 genes in autosomal forms." (PMID 40004525, 2025). "Nevertheless, pathogenic variants in the COL4A5 gene can cause Alport syndrome (OMIM: 301050): a condition characterized by kidney disease, hearing loss, eye anomalies, and TAAD." (PMID 39125885, 2024). "The Slavic variant in the COL4A5 gene, c.1871G>A (p.Gly624Asp), is linked with a mild course of Alport syndrome." (PMID 39273284, 2024). "Classical progressive X-linked Alport syndrome occurs in males with hemizygous COL4A5 variants because their one and only X chromosome carries a pathogenic variant." (PMID 37180518, 2023). "Currently, there are lingering questions regarding the possibility of another gene in the Xq22 region playing a role in Alport syndrome or the potential presence of hidden mutations within the COL4A5 gene, possibly within introns." (PMID 38021591, 2023). "The major gene that causes Alport syndrome is COL4A5, which encodes the collagen IV α5 chain, with X-linked inheritance." (PMID 36732323, 2023). "More than 1000 mutations have been identified in the COL4A3, COL4A4, and COL4A5 genes leading to a reclassification of Alport syndrome and thin basement membrane nephropathy as type IV collagen nephropathies." (PMID 37180518, 2023). "Most male X-linked Alport syndrome patients with COL4A5 nonsense mutations experience end-stage kidney failure by 30 years old." (PMID 37928459, 2023). "The mutations in COL4A3/COL4A5 were implicated in the pathogenesis of Alport syndrome and thin basement membrane disease (TBMD)." (PMID 38202130, 2023). "X-linked Alport syndrome (XLAS) caused by pathogenic variants in COL4A5 gen accounts for less than 80% of patients with Alport syndrome." (PMID 36982595, 2023). "A genetic test confirmed a novel hemizygous nonsense variant COL4A5 c.2980G > T (p.Gly994Ter), and he was diagnosed with X-linked Alport syndrome." (PMID 37928459, 2023). "The α5 subunit is encoded by COL4A5, located on the X-chromosome, and is associated with the classic X-linked Alport syndrome (AS) in male patients." (PMID 36981034, 2023). "There exist three forms of this disease which include: (i) X-linked Alport syndrome, which is the most common and arises due to the mutation in COL4A5 on chromosome X, (ii) Autosomal recessive Alport syndrome, and (iii) Autosomal dominant Alport syndrome." (PMID 38021591, 2023).
Alport syndrome (continued). "Pathogenic variants in COL4A5 are responsible for the severe X-linked glomerulopathy, Alport syndrome (AS), while homozygous or compound heterozygous variants in the COL4A3 or the COL4A4 gene cause autosomal recessive AS." (PMID 37761826, 2023). "The correlation between COL4A5 variant location, type and phenotype has been less clear for females with X-linked Alport syndrome." (PMID 35602506, 2022). "X-linked Alport syndrome is a genetic kidney disease caused by pathogenic COL4A5 variants, but little is known of the consequences of missense variants affecting the NC1 domain of the corresponding collagen IV α5 chain." (PMID 35789182, 2022). "Currently, three disease-causing genes, namely collagen type IV alpha 3–5 (COL4A3, COL4A4, and COL4A5), have been associated with the occurrence of Alport syndrome." (PMID 36159970, 2022). "Pathogenic COL4A5 variants affecting Gly in the Leiden Open Variation Database in males with X-linked Alport syndrome were correlated with age at kidney failure (n = 157) and hearing loss diagnosis (n = 80)." (PMID 35177655, 2022). "Pathogenic variants in COL4A5 usually cause X-linked Alport syndrome (XLAS), whereas those in the COL4A3 or COL4A4 genes are associated with autosomal dominant (AD) or recessive (AR) inheritance." (PMID 35419377, 2022). "X-linked Alport syndrome results from pathogenic variants in COL4A5 and is the cause of severe disease." (PMID 35789182, 2022). "Pathogenic variants in the COL4A5, which encodes the type IV collagen α5 chain, are known to cause X-linked Alport syndrome (XLAS); XLAS is the most common inherited form of AS with ~80% of all AS patients." (PMID 35211492, 2022). "X-linked Alport syndrome (XLAS) is caused by pathogenic variants in COL4A5 and is characterized by progressive kidney disease, hearing loss, and ocular abnormalities." (PMID 35211492, 2022). "X-linked Alport syndrome due to pathogenic COL4A5 variants is the commonest inheritance pattern that causes severe disease." (PMID 36531881, 2022). "Pathogenic variants in COL4A5 usually cause X-linked Alport syndrome (XLAS), while alterations in COL4A3 and COL4A4 genes are associated with autosomal dominant AS (ADAS) or autosomal recessive AS (ARAS)." (PMID 35419377, 2022). "X-linked Alport syndrome (XLAS) due to COL4A5 disease-causing variants is the most common form and accounts for 85%." (PMID 35360741, 2022). "X-linked Alport syndrome (AS) caused by hemizygous disease-causing variants in COL4A5 primarily affects males." (PMID 36341250, 2022). "X-linked Alport syndrome accounts for the majority of Alport syndrome cases, arising from mutations in the COL4A5 gene." (PMID 34238373, 2021). "We found that metformin or losartan protected Col4a5 G5X Alport syndrome mice against Alport syndrome-induced podocyte loss, which was evaluated by staining with the podocyte marker WT1." (PMID 33782421, 2021). "It is reported that 90% of patients develop ESRD by the age of 30 years in males with X-linked Alport syndrome (XLAS) due to variants in COL4A5 gene." (PMID 34209341, 2021). "With the rapid development of molecular genetic testing, Alport syndrome causes have been restricted mostly to variants in the COL4A5 or COL4A3/COL4A4 genes." (PMID 34238373, 2021). "In family FAM618 we identified a novel variant p.Gly472Glu in the COL4A5 gene (NM_000495.5) in two affected siblings (D815, D817), both of whom showed a clinical picture of Alport syndrome." (PMID 34795337, 2021). "Encoded by the collagen type IV alpha-3 (COL4A3), alpha-4 (COL4A4), and alpha-5 (COL4A5) genes, Alport syndrome (AS) is a rare inherited renal disease caused by abnormalities of the α3, α4, or α5 chains in type IV collagen." (PMID 33748275, 2021). "To date, about 85% of patients are diagnosed with X-linked Alport syndrome (XLAS) caused by pathogenic variants in the COL4A5 gene." (PMID 33772369, 2021).
Alport syndrome (continued). "Alport syndrome-diffuse leiomyomatosis is a rare type of X-linked Alport syndrome resulting from contiguous deletions of 5′ exons of COL4A5 and COL4A6." (PMID 34778325, 2021). "Hundreds of mutations in LAMB2, COL4A3, COL4A4 and COL4A5 have been reported to cause the human kidney diseases Pierson syndrome, Alport syndrome and thin basement membrane nephropathy." (PMID 33745160, 2021). "The COL4A5 gene is associated with X-linked Alport syndrome characterized by SN HL, as well as ocular and kidney involvement." (PMID 34440452, 2021). "Jeffrey Miner (St Louis) concluded the proceedings with his latest work on mutations in matrix genes including COL4A5, which are implicated in Alport syndrome." (PMID 33745160, 2021). "Parents of HL children with COL4A5 variants should be made aware that alleles of this gene are associated with Alport syndrome." (PMID 32842620, 2020). "X-linked Alport syndrome (XLAS) is caused by mutations in the COL4A5 gene and is the most common form of Alport syndrome." (PMID 32117450, 2020). "COL4A5 is one of the causative genes in Alport Syndrome, a genetic condition characterized by progressive loss of kidney function, hearing, and eye abnormalities, including misshapen lenses and abnormal retina." (PMID 32883240, 2020). "The same hemizygous COL4A5 gene mutations, identified in peripheral blood, were detected in Alport syndrome fibroblasts and iPSCs." (PMID 32117450, 2020). "In this study, dermal fibroblasts from Alport syndrome patients with different COL4A5 gene mutations were reprogrammed into iPSCs." (PMID 32117450, 2020). "The most frequent are mutations in the COL4A5 gene and are the cause of X-linked Alport syndrome (XLAS) (OMIM301050), a semi-dominantly inherited renal disease." (PMID 33233744, 2020). "The COL4A5 (p.Gly624Asp) mutation in female cases was manifested by the development of early childhood hematuria with normal hearing, which is consistent with X-linked Alport syndrome in females." (PMID 33233744, 2020). "We obtained human dermal fibroblasts from three patients with X-linked Alport syndrome (harboring missense, splicing and frameshift mutations in the COL4A5 gene) and one healthy control (WT), and generated patient-specific and WT iPSCs." (PMID 32117450, 2020). "we reported an adult man with the coexistence of rheumatoid arthritis and Alport syndrome with the missense mutation in COL4A5 (c.1351 T > C, p.Cys451Arg)." (PMID 31337345, 2019). "A single mutation in the COL4A4 gene was detected in three male and 10 female patients, a single COL4A3 gene mutation was detected in two male and two female patients, and X-linked Alport syndrome (COL4A5 gene mutation) was detected in four male patients." (PMID 30805210, 2019). "In this study, among 417 patients diagnosed or suspected of Alport syndrome in our department during 2014–2017, six were identified with pathogenic variants in COL4A5 plus heterozygous pathogenic variants in COL4A3 or COL4A4, which accounted for 1%." (PMID 30883042, 2019). "About 85% of individuals with Alport syndrome are X‐linked inherited due to mutations in the COL4A5 gene." (PMID 30883042, 2019). "COL4A5 is one of the major components of the glomerular basement membrane, and its mutation or aberration is involved in Alport syndrome and uterine leiomyomas." (PMID 31803620, 2019). "Seven patients had NPHS1 gene mutations, and 1 (case 6) had both NPHS1 and COL4A5 (the gene that causes Alport syndrome) mutations." (PMID 31456999, 2019). "The father of patient 120F (120F-Fa) with a c.2365A>C (p.T789P) variant in COL4A5 associated with X-linked Alport syndrome (MIM:301050), was reported to have a renal defect." (PMID 31349857, 2019). "Mutations in COL4A5 cause classical X-linked Alport Syndrome, while rare mutations in the LAMA5 have been reported in patients with focal segmental glomerulosclerosis." (PMID 29764427, 2018).